EGFR (epidermal growth factor receptor)
Diseases named in the same sentence as EGFR in open-access papers (continued):
Sharing a sentence is not in itself a finding about the gene and the disease.
lung cancer (continued). "Acquired resistance to EGFR-TKI in lung cancer remains a major problem to be solved in clinical practice." (PMID 36760347, 2023). "EGFR-mutant lung cancers develop a wide range of potential resistance alterations under therapy with the third-generation EGFR tyrosine kinase inhibitor osimertinib." (PMID 37887535, 2023). "The development of EGFR tyrosine kinase inhibitors (EGFR-TKIs) has revolutionized the treatment of lung cancer." (PMID 37122754, 2023). "The EGFR signaling pathway is overactive in several cancers (e.g., lung cancer, colon cancer) and a number of selective inhibitors of EGFR tyrosine kinase are in clinical use for cancer therapy." (PMID 37834119, 2023). "To verify the expression of LINC00969 in gefitinib resistant lung cancer, we collected 36 tissue specimens from patients with advanced NSCLC harbour EGFR exon 19 deletion (Exon 19 Del) or a point mutation in exon 21 (Exon 21 L858R)." (PMID 37156816, 2023). "Epidermal growth factor receptor (EGFR) is a transmembrane protein that is highly expressed in lung cancer, liver cancer, bladder cancer, breast cancer, and other malignant tumors." (PMID 36980923, 2023). "Studies reported that exosomal proteins found in patient serum and urine, such as LRP1, EGFR and LG3BP, have been associated to lung cancer stage and metastasis." (PMID 37400751, 2023). "Specifically, epidermal growth factor receptor (EGFR) inhibitors are clearly effective clinically in the treatment of EGFR mutant lung cancer, and HER2 inhibitors are active in HER2-positive breast cancer." (PMID 37169023, 2023). "In this study, we demonstrated that BC overexpression in lung cancer cells reduced cellular sensitivity to the EGFR‐TKIs gefitinib, afatinib and osimertinib." (PMID 36650118, 2023). "The same study demonstrates that CAR enables A549 lung cancer cell proliferation through binding to the microtubule associated protein KIF22 that promotes activation and delayed internalisation of Epidermal Growth Factor Receptor (EGFR;)." (PMID 37306404, 2023). "In this study, our data has demonstrated that extrinsic AICAR treatment induces apoptosis and increases DNA damage in EGFR-mutant lung cancer cell lines." (PMID 36810913, 2023). "The effects of long‐term exposure on EGFR activation were also examined at different times of continuous exposure to PM2.5 at 50 μg/ml in lung cancer cells." (PMID 36975376, 2023). "The higher success rates of precision medicine in treating HER2-positive breast cancer and EGFR-positive lung cancer highlight its potential to widely change clinical practice." (PMID 38048216, 2023). "Our findings support to use tissue and liquid rebiopsy in parallel after EGFR‐TKI resistance in lung cancer." (PMID 38140788, 2023). "According to recent research, prior β-blocker usage is related to prolonged time-to-discontinuation (TTD) and survival rates (OS) in treatment-naive patients who have advanced lung cancer following first-line EGFR-TKIs67." (PMID 37193898, 2023). "EGFR is recognized to be closely related to the occurrence of lung cancer, and epidermal growth factor tyrosine kinase inhibitors (EGFR-TKIs) have been widely used to treat EGFR-mutant NSCLC." (PMID 36870024, 2023). "We have presented data on testing and treatment patterns of EGFR- and ALK-mutated lung cancer on a national level." (PMID 36900294, 2023). "The activation of EGF like domain multiple 7 (EGFL7)/Notch signalling in lung cancer cells, triggers resistance to EGFR inhibitors." (PMID 37569598, 2023). "RET fusion-positive lung carcinomas exhibit poorer differentiated tumors compared to those with ALK or EGFR alterations." (PMID 38132167, 2023). "In one lung cancer patient, the amplification of EGFR KDD in the prior treatment sample indicated the involvement of EGFR KDD in afatinib resistance." (PMID 36325957, 2023).
lung cancer (continued). "Based on the data obtained, it can be inferred that the novel compounds, as well as their key intermediate, compound 5, demonstrated potent anticancer activity against lung carcinoma by inhibiting EGFR." (PMID 37298747, 2023). "Gefitinib and erlotinib are cancer drugs which have a common chemical backbone structure, and they are commonly used as EGFR-tyrosine kinase inhibitors in lung carcinoma." (PMID 37779898, 2023). "We then tested the lung carcinoma cell lines A549 (WT EGFR) and H1975 (T790M EGFR), the immortalized breast epithelial line MCF10A and parental CHO cells that lack EGFR expression with cSNX1.3, cPTD4 control, or Sapitinib." (PMID 36253541, 2023). "In lung carcinomas efforts are being indeed made to overcome primary or acquired resistance to EGFR inhibitors, but these alternative therapeutic approaches still need further preclinical investigations." (PMID 37041632, 2023). "The observation aligns with the finding that RET fusion-positive lung carcinomas displayed a higher prevalence of poorly differentiated tumors in comparison to those with ALK or EGFR alterations." (PMID 38132167, 2023). "Here, we encountered a lung cancer patient with complex EGFR (L858R and E709X) and CTNNB1 comutations who successfully responded to afatinib." (PMID 36519636, 2022). "Another study of non-small cell lung cancer demonstrated that the blockade of EGFR or MAPK signaling protected the lung cancer cells from ferroptosis." (PMID 35359830, 2022). "Apoptosis is induced by the Akt-NF-κB pathway in lung cancer cells, and the EGFR-mediated Ras-Raf-MEK-ERK pathway in breast cancer cells." (PMID 36547923, 2022). "Our data indicate that purine metabolism is relevant to acquiring drug tolerance to EGFR TKIs in lung cancer." (PMID 35840668, 2022). "The researchers used Sortase A and OaAEP1, protein ligating enzymes, to conjugate EVs with anti-EGFR antibodies to achieve targeted delivery to EGFR positive lung cancer cells and mice." (PMID 36277506, 2022). "Although the mechanisms of EGFR-TKI resistance are complex and incompletely understood, abnormal activation of PI3K/AKT is the explicit mechanism leading to EGFR-TKI resistance in lung cancer cells." (PMID 36209201, 2022). "Recent studies have sought to evaluate early oncogenic signaling in EGFR-mutant lung cancers under EGFR-TKI treatment, but few studies have evaluated the effect of the tumor microenvironment on persistent tumor cells under EGFR-TKI treatment." (PMID 36612121, 2022). "The online analysis portal enables the setup of such resistance-associated signatures for each available drug in an automated manner – see, for example, a previous signature of resistance against EGFR inhibitors manually identified in lung cancer." (PMID 35765648, 2022). "The imaging of EGFR signaling pathway activity was performed in A549 lung cancer cells using the modified ETTE nanoprobes as imaging agents." (PMID 35105871, 2022). "This study aimed to compare the anti-cancer efficacy of EGFR inhibitors (gefitinib and erlotinib) alone and in combination with nutritional supplements of Se/FO in treating lung cancer." (PMID 36547898, 2022). "Identifying the potential key factors of drug resistance to EGFR-TKIs is essential to treat patients with EGFR mutant lung cancer." (PMID 35463301, 2022). "Despite a higher positive correlation (Pearson correlation coefficient R ≈ 0.84), we determined several known lung cancer-associated genes with high RS and low |log2FC|, such as TRIM28, APP, ESR1, MYC, and EGFR." (PMID 36229842, 2022). "Compared with the newly diagnosed, untreated lung cancer group, there were significant changes in carnitine, amino acids, fatty acids, and lipids in the EGFR-TKI- and PD-1/PD-L1 inhibitor-treated groups." (PMID 36034789, 2022). "For validation in clinical cases, we measured these gene alterations in plasma circulating tumor DNA (ctDNA) before and 8 weeks after starting EGFR-TKIs in four patients with EGFR-mutant lung cancer." (PMID 35326664, 2022).
lung cancer (continued). "A series of tyrosine kinase inhibitors have been developed that treat these EGFR positive lung cancers, with remarkable efficacy." (PMID 36054194, 2022). "The advent of molecular profiling has revolutionized the treatment of lung cancer by comprehensively delineating the genomic landscape of the epidermal growth factor receptor (EGFR) gene." (PMID 35209919, 2022). "Our results suggest therefore that cetuximab can induce ICD of HNSCC cells, which is consistent with previous observations on murine lung cancer cell line and on murine colon cell line expressing a human EGFR." (PMID 36139440, 2022). "In EGFR mutant lung cancer patients, SREBP-1 expression promoted drug resistance mainly through upregulated and sustained lipogenesis." (PMID 35884561, 2022). "Numerous studies have demonstrated the benefit of EGFR TKI plus EGFR mAbs in lung cancer using in vitro and in vivo model systems." (PMID 35903676, 2022). "We further demonstrate that ND-Cet selectively binds to EGFR in clinical patient PLC26 lung cancer cells." (PMID 36678740, 2022). "Emerging evidence support the idea that 1,25-dihydroxyvitamin D3 (1,25(OH)2D3, 1,25D, calcitriol) inhibits lung cancer cell proliferation and opposes erlotinib or osimertinib resistance in preclinical models or in EGFR-mutant LUAD patients." (PMID 35301287, 2022). "Certain quinazolin-4(3H)-one derivatives exert potent growth-inhibitory activity in lung cancer cell lines by binding to the active site of EGFR." (PMID 35745617, 2022). "Since EGFR is the key driver of lung cancer and can regulate the expression of various genes, therefore we analyzed the correlation between EGFR and NEDD4L." (PMID 35090513, 2022). "Overexpressed ERα in NSCLC patients was correlated with smoking, and overexpression of both the EGFR and ERα in NCLSC patients was associated with poor prognosis, establishing it as a useful prognostic factor in lung cancer." (PMID 35631448, 2022). "We hope that this deep learning-based model will aid doctors in identifying suitable advanced lung cancer patients for EGFR-targeted therapy, allowing for more efficient and convenient application of precise medicine." (PMID 36300191, 2022). "In epidermal growth factor receptor (EGFR) T790M mutant lung cancer cells, which exhibit resistance to the EGFR inhibitor erlotinib, significantly reduced cellular glutathione levels are observed compared to erlotinib-sensitive cells." (PMID 35011702, 2022). "Another study, which used an ELISA assay to measure and compare EGFR serum protein and circulating mRNA levels, found that both the protein serum level and gene expression of EGFR were higher in patients with lung cancer." (PMID 35053080, 2022). "They found that in the presence of monocytes or macrophages the bispecific mAb mediated killing of lung cancer cell lines, and the principal cytotoxic mechanism was trogocytosis, which resulted in the downregulation of both EGFR and cMet." (PMID 35892705, 2022). "We have also described an EV surface functionalization approach that facilitates EGFR‐targeted delivery of paclitaxel‐loaded RBCEVs to EGFR‐positive lung cancer cells and increases treatment efficacy in vivo." (PMID 35430766, 2022). "In conclusion, our findings suggest that the natural product MA promotes EGFR-TKI sensitivity in lung cancer cells and is a potential EGFR-TKI sensitizer." (PMID 36712673, 2022). "Tracking of a single EGFR molecule by ND-Cet will provide for understating the function and regulation of EGFR in human lung cancer." (PMID 36678740, 2022). "Regarding immune checkpoint inhibitors direct efficacy in Exon 20 insertion mutant lung cancers, data from retrospective studies suggested similar outcomes as compared to wild-type historical control, and better than classical EGFR mutant patient." (PMID 35785671, 2022). "Since EGFR regulates multiple oncogenic pathways in lung cancer, we tried to clarify through which pathway it positively regulates BMI1." (PMID 35794816, 2022).
lung cancer (continued). "Together, our results suggest that there is crosstalk among cytokines, tumor cells, and the immune microenvironment, and they highlight the paradoxical oncogenic properties of CXCL10 in EGFR-mutant lung cancer during EGFR-TKI therapy." (PMID 36612121, 2022). "At a NIR-PTT energy level that has a minimal cytotoxic effect, PIA-NC significantly sensitizes EGFR-overexpressing A549 lung cancer cells to NIR-PTT-induced cytotoxicity at a rate of 70%, but in EGFR-negative 3T3 fibroblasts the rate was 30%." (PMID 36291827, 2022). "On the one hand, BPA has been shown to increase the migration of lung cancer cells through the GPER/EGFR/ERK1/2 signalling pathway and increase the migration of triple-negative breast cancer cells through ERRγ." (PMID 36011004, 2022). "EGFR inhibitors are often utilized for the treatment of EGFR-mutant lung cancer patients; however, acquired drug resistance has reduced its efficacy." (PMID 36233210, 2022). "For instance, EGFR inhibitors block both the PI3K and MEK pathway in EGFR-mutant lung cancers, and resistance can occur when either of these pathways is reactivated." (PMID 36506869, 2022). "To ensure the recommendation system captures clinical evidence, we included genomic data from osimertinib-treated EGFR-mutant lung cancer patients in the feature set." (PMID 35351890, 2022). "In EGFR-mutant lung cancer, EMT inhibits BIM through EMT-inducing transcription factors, ZEB1, and TWIST1, and becomes resistant to EGFR-TKIs19–21." (PMID 35790819, 2022). "Among the four compounds, NSC609077 showed a significant inhibitory effect on the EGFR activity and inhibited lung cancer cell viability, proliferation, and migration by suppressing EGFR-related signaling pathways." (PMID 35408854, 2022). "Among these compounds, three compounds, NSC342715, NSC622394, and NSC609077, inhibited the phosphorylation of EGFR by 50% in the gefitinib-resistant H1975 lung cancer cell line." (PMID 35408854, 2022). "High D-dimer plasma induced resistance to gefitinib, erlotinib, afatinib, or osimertinib in EGFR mutant lung cancer cells." (PMID 35756605, 2022). "The Iressa Pan‐Asia Study (IPASS) established the crucial role of epidermal growth factor receptor (EGFR) in the progression of lung cancer, which has initiated a new direction to individualize and design clinical treatment of lung cancer patients." (PMID 34766737, 2022). "Although previous studies on EGFR have primarily focused on other diseases such as lung cancer, there is increasing evidence to suggest that the EGFR signaling pathway occupies a crucial role in vascular diseases." (PMID 34729926, 2022). "Genetic alterations of the PI3K, AKT, PTEN, EGFR, and KRAS genes, MET amplification, and EML4-ALK rearrangements are associated with lung cancer progression." (PMID 36230484, 2022). "In our previous study, we identified several PD-L1 variants (PD-L1–v242 and –v229) in samples from anti–PD-L1–treated lung cancer patients (LUSC and EGFR-mutated lung adenocarcinoma)." (PMID 34874919, 2022). "When compared to the conventional cell line, the results revealed that these nanoparticles targeted overexpressed EGFR lung cancer cells (A549) with great specificity compared to (MRC-5) cells." (PMID 36085575, 2022). "The histone deacetylase (HDAC) inhibitor vorinostat promotes ferroptosis through downregulating xCT, resulting in a dramatic increase in hydroperoxides in EGFR-mutant lung cancer cells." (PMID 35847022, 2022). "Although the emergence of EGFR-TKIs has brought a revolutionary breakthrough in the treatment of lung cancer, the disease still progresses after 9–11 months of treatment with EGFR-TKIs." (PMID 35431966, 2022). "The overall objective tumor response rate was 51%, indicating that AZD9291 was highly effective in patients with EGFR (T790M) mutant lung cancer whose disease had progressed during previous treatment with EGFR tyrosine kinase inhibitors." (PMID 35922812, 2022).
lung cancer (continued). "A typical study targeting EGFR (Epidermal Growth Factor Receptor) mutant lung cancer cells with MSNs has been conducted." (PMID 35875329, 2022). "In lung cancer, the alteration of upstream regulators, such as activating the epidermal growth factor receptor (EGFR) can lead to sustained activation of the PI3K/Akt/mTOR cascade." (PMID 36180880, 2022). "C.M.L. was also supported in part by EGFR RESISTERS/LUNGEVITY Lung Cancer Research Award, P30-CA086485, UG1CA233259, 5P01CA129243, and The Phran Galante Research Funds." (PMID 35867821, 2022). "Preclinical studies have shown that PD-1 inhibitors improve the survival of mice with EGFR-driven lung cancer by enhancing T-cell function." (PMID 36159860, 2022). "ALK mutations are mutually exclusive with EGFR and KRAS mutations in many patients, positioning ALK as the primary target for treatment in ALK-positive lung cancers." (PMID 36230484, 2022). "Beyond tumorigenesis, recent studies have investigated dysregulated ncRNAs in EGFR TKI-resistant lung cancer and partially elucidated their diverse mechanisms." (PMID 36139582, 2022). "Initially, EGFR was regarded as a target of lung cancer only, however, through recent studies it was revealed that EGFR also plays a role in the progression of TNBC." (PMID 35631368, 2022). "The Iressa Pan-Asia Study (IPASS) showed that EGFR tyrosine kinase inhibitors (EGFR-TKIs) significantly prolonged the survival of NSCLC patients harboring EGFR mutations, a finding that revolutionized the treatment of lung cancer." (PMID 36164607, 2022). "The disruption of EGFR by inhibiting UP8 was reported to overcome gefitinib resistance in lung cancer." (PMID 36338727, 2022). "In comparison to PC9 cells, the EGFR mutant non–small cell lung cancer (NSCLC) cells HCC4006, HCC827, and H1975 have higher levels of baseline STAT1 expression." (PMID 35089788, 2022). "We aimed to identify, among clinically measurable factors, independent predictors of progression‐free survival of patients who received osimertinib as first‐line treatment for EGFR‐mutant advanced non‐small cell lung cancer." (PMID 36082812, 2022). "In particular, previous reports have suggested that autophagy plays a role in EGFR-TKI osimertinib therapy for lung cancer." (PMID 35459209, 2022). "Drug resistance caused by EGFR mutations and genetic polymorphisms of drug metabolizing enzymes and transporters impedes effective treatment of EGFR mutant and resistant lung cancer." (PMID 35209919, 2022). "Torsades de Pointes (TdP) occurred in a 68-year-old female with epidermal growth factor receptor (EGFR) mutant lung cancer administered osimertinib, the third-generation EGFR tyrosine kinase inhibitor (TKI)." (PMID 35711361, 2022). "Somatic EGFR kinase domain mutations (EGFRMT) are detected in 10%–20% and 30%–60% of White and Asian non–small cell lung cancer (NSCLC) patients, respectively, leading to constitutive EGFR kinase activation." (PMID 35708914, 2022). "The reported degraders displayed potent and selective antitumour activities in EGFR-TKI-resistant lung cancer cells." (PMID 35702041, 2022). "Here, the clinical implications of ncRNAs in EGFR-mutant lung cancer are listed with examples to offer a useful reference for clinical decision-making." (PMID 36139582, 2022).